TLR4 (toll like receptor 4)
Diseases named in the same sentence as TLR4 in open-access papers (continued):
Sharing a sentence is not in itself a finding about the gene and the disease.
fungal keratitis (3 papers, 2019 to 2025). "Previous studies have shown that TLR4 activation effectively facilitates the production of proinflammatory cytokines in fungal keratitis, making TLR4 a key target for modulating the inflammatory response in this condition." (PMID 41425966, 2025). "This was corroborated by results of real-time PCR at mRNA levels of TLR4, TNFα and IL-1β, as well as the ELISA results at protein levels of TNFα and IL-1β of the corneal specimens from mice with fungal keratitis." (PMID 31285488, 2019). "In the current study, we found that there was abundant expression of TNFα and TLR4 in the specimens from patients with fungal keratitis and mice with experimental fungal keratitis." (PMID 31285488, 2019). "In the current study, we investigated the expression of histone H3 (H3), acetylated histone H3 (AC-H3), HDAC1, TLR4, TNFα, and IL-1β in corneal specimens from patients with fungal keratitis and mice with experimental fungal keratitis." (PMID 31285488, 2019). "It was found that the expression of mRNA of TLR4, TNFα and IL-1β of the corneal specimens from mice with fungal keratitis was significantly suppressed after SAHA treatment compared with control, the production of TNFα and IL-1β was also inhibited with SAHA treatment as shown by ELISA assay." (PMID 31285488, 2019). "SAHA was able to inhibit experimental fungal keratitis in mouse by suppressing TLR4 and inflammatory cytokines such as TNFα and IL-1β; the inhibition of HDAC may be a potential therapeutic approach for the treatment of fungal keratitis." (PMID 31285488, 2019). "SAHA was able to inhibit experimental fungal keratitis by suppressing TLR4 and inflammatory cytokines (TNFα, IL-1β) and inhibition of HDAC may be a potential therapeutic approach for the treatment of fungal keratitis." (PMID 31285488, 2019).
gallbladder cancer (3 papers, 2016 to 2024). "Furthermore, miR-146b-5p inhibits tumorigenesis and metastasis of gall bladder cancer by targeting toll-like receptor 4 via the NF-κB pathway." (PMID 35805086, 2022). "Multiple polymorphisms in genesassociated with the immune system, inflammation, and oxidative stress that have been linkedto the development of gallbladder cancer like PTGS2, TLR2, TLR4, IL1RN, IL10, IL8, CCR5,LXRB, and OGG1." (PMID 28105075, 2016).
gastroesophageal reflux (3 papers, 2020 to 2021). "We hypothesized that TLR2, TLR4 and FXR activate during gastroesophageal reflux and modulate the mucosal injury." (PMID 33686512, 2021).
glomerular disease (3 papers, 2018 to 2021). "As TLR4 is expressed on podocytes and is upregulated in glomerular disease, we isolated and cultured primary podocytes from WT and Twist1-PKO animals and then stimulated TLR4 on the podocytes with LPS for 6 hours to mimic the podocyte activation that occurs during inflammatory injury." (PMID 34369383, 2021). "It has been reported that endogenous agonists of TLR-4 were present in glomerular diseases that may induce podocyte dysfunction independent of TIL7/9 activation seen with endocytosed DNA and RNA immune complexes in SLE." (PMID 29988544, 2018).
Graves disease (3 papers, 2016 to 2022). Graves' disease is an autoimmune disorder that leads to overactivity of the thyroid gland (hyperthyroidism).It is caused by an abnormal immune system response that causes the thyroid gland to produce too much thyroid hormones. "Thus the TLR-2 and TLR-4 can be a prognostic marker for Graves’ disease." (PMID 31554206, 2019).
HELLP syndrome (3 papers, 2008 to 2022). A life-threatening condition that can potentially complicate pregnancy. "Highest frequencies for TLR4 variants were observed in women who developed HELLP syndrome (adjusted OR 4.1 [95% CI 1.7–9.8])." (PMID 18382655, 2008). "The highest frequency of the TLR-4 was observed in women who developed the HELLP syndrome (adjusted OR 4.1)." (PMID 24991435, 2014). "Our data suggest that exogenous (infectious) agents involved in the TLR4 pathway, might be candidate factors triggering HELLP syndrome within the already immuno-modulated pre-eclamptic patient." (PMID 18382655, 2008). "Genes involved in innate immunity, such as Toll-like receptor 4 (TLR4), oligomerization domain 2 (NOD2), and tumor necrosis factor (TNF)-alpha, among others, have been found to be associated with early-onset PE, HELLP syndrome, and severe FGR complicated by PE." (PMID 36313546, 2022).
hypercoagulability (3 papers, 2021 to 2025). "This underscores the importance of investigating novel therapeutic targets such as targeting TLR4 signaling or its downstream cAMP/cGMP pathway to restore prostaglandin-dependent inhibitory signaling and mitigate platelet-driven hypercoagulability in cats with high thrombotic risk." (PMID 41574253, 2025). "The absence of ACE2 results in ensuing angiotensin II overproduction, which may trigger complement activation, Toll-like receptor 4 (TLR4) activation, hypercoagulability, and microangiopathy." (PMID 34069451, 2021).
hypothyroidism (3 papers, 2017 to 2025). Abnormally low levels of thyroid hormone. "Heat exposure increases intestinal permeability and endotoxin translocation, triggering TLR4-mediated inflammation and temporary hypothyroidism." (PMID 41515177, 2025).
Impaired glucose tolerance (3 papers, 2015 to 2024). An abnormal resistance to glucose, i.e., a reduction in the ability to maintain glucose levels in the blood stream within normal limits following oral or intravenous administration of glucose. "Deng verified that adipose Ti-EVs significantly enhanced the development of IR, impaired glucose tolerance, and induced inflammatory cytokines in a toll-like receptor 4 (TLR4)-dependent manner, which would increase cancer incidence." (PMID 38598014, 2024).
infectious mononucleosis (3 papers, 2016 to 2021). A condition characterized by an increase in mononuclear white blood cells and swollen lymph nodes, which is usually caused by infection with the Epstein-Barr virus. "Individuals with SNP at TLR4 896 A/G (rs4986790) and TLR9 1174 G/A (rs352139) had a higher risk of the infectious mononucleosis and clinical outcomes when compared with subjects with the wild-type genotype." (PMID 34578364, 2021).
inflammatory skin disease (3 papers, 2015 to 2021). Inflammatory skin disorders covers a broad category that includes many conditions ranging in severity, from mild itching to grave medical health complications These disorders are common in people of all ages and races. "When activated macrophages are affected by UVB-irradiated keratinocytes, they activate the TLR2 and TLR4 pathways and cause inflammatory skin diseases." (PMID 33670841, 2021).
intervertebral disc degeneration (3 papers, 2020 to 2023). "Hypoxia-induced miR-17-5p enrichment in MSCs-sEVs, which in turn regulated the proliferation and synthesis of myeloid cell (NPC) stroma through the TLR4/PI3K/AKT pathway of the downstream target gene TLR4 for the treatment of intervertebral disc degeneration (IDD)." (PMID 36768406, 2023).
intestinal cancer (3 papers, 2017 to 2024). "In summary, the interplay between the LPS/TLR4 signaling pathway and various metabolic pathways significantly contributes to chronic intestinal inflammation onset and intestinal cancer progression." (PMID 38930793, 2024). "TLR4 signaling activation induces intestinal inflammation and supports bowel cancer development." (PMID 38930793, 2024).
invasive breast carcinoma (3 papers, 2021 to 2024). A carcinoma that infiltrates the breast parenchyma. "To analyze the clinical significance of S100A7 and TLR4 in invasive breast cancer, we analyzed the expression of S100A7 and TLR4 by using the publically available TISIDB database." (PMID 33969603, 2022). "The expression levels of the NLRP3, PYCARD and TLR4 were determined by immunohistochemistry in a cohort of primary invasive breast carcinomas (BCs)." (PMID 34540671, 2021). "Taken together, these findings revealed that a high level of S100A7 and low expression of TLR4 could serve as poor prognostic markers for invasive breast cancer patients, especially basal or metastatic breast cancer." (PMID 33969603, 2022). "Consequently, elevated levels of S100A7 and reduced expression of TLR4 could serve as indicators of poor prognosis for invasive breast cancer." (PMID 39830522, 2024). "Altogether, our study reports a novel role of LPS in driving S100A7 expression for modulating the expression of TLR4 and RAGE, which demands further exploration of this regulatory axis for drug intervention of invasive breast cancers." (PMID 33969603, 2022).
ischemic disease (3 papers, 2015 to 2022). Lack of blood supply to an area of the body, resulting in impairment of tissue oxygenation. "In addition, BA can alleviate oxygen-glucose-deprived challenged microglia injury in ischemic diseases by attenuating expression of inflammatory cytokines TNF-α, IL-1β, IL-6, and IL-8 through TLR4 pathway." (PMID 36408278, 2022).
joint disease (3 papers, 2015 to 2024). "The same group enhanced their research by focusing on the TLR4 involvement in the pathogenesis of MPS bone and joint disease." (PMID 35216110, 2022). "Overall, these findings suggest the implication of the TLR4/TNF-α signalling pathway in MPS bone and joint disease, and the TLR4/IL-1 in neurodegeneration." (PMID 35216110, 2022). "A current model for the findings in MPS joint disease hypothesizes that accumulated glycosaminoglycans (GAG) bind to and activate toll-like receptor 4 (TLR4) leading to expression of TNF-α and matrix metalloproteinases." (PMID 38173710, 2024). "Finally, the bone and joint disease correction and lack of secondary storage-mediated amplification following TLR4 knock-out in MPS VII mice further proves the pivotal role of TNF-α in the periphery, as opposed to IL-1β." (PMID 35216110, 2022).
juvenile idiopathic arthritis (3 papers, 2017 to 2024). Juvenile idiopathic arthritis (JIA) is the term used to describe a group of inflammatory articular disorders of unknown cause that begin before the age of 16 and last over 6 weeks. "In another study, researcher aimed to evaluate whether a potential relationship might exist between S100A12, Toll-like receptor 4 (TLR4) and the disease activity of both FMF and juvenile idiopathic arthritis (JIA)." (PMID 39132307, 2024).
keloid (3 papers, 2018 to 2024). An irregularly shaped, elevated mark on the skin caused by deposits of excessive amounts of collagen during wound healing. "NLRP3 inflammasome is often stimulated by high mobility group box 1 (HMGB1), Toll-like receptor (TLR4), NF-κB, and reactive oxygen species known to be increased in keloid." (PMID 33126764, 2020). "We also discovered an extracellular excess of HMGB1 and an increase in the levels of the HMGB1 receptors RAGE and TLR4 in the keloid tissue compared with the adjacent normal skin." (PMID 29849053, 2018). "Compared with extra-lesional normal tissue, markedly increased HMGB1, RAGE, and TLR4 immunoreactivity was noted in the central and peripheral keloid regions." (PMID 29849053, 2018). "We carried out immunohistochemical staining to investigate the expression patterns of HMGB1 and its receptors (RAGE and TLR4 proteins) in keloid tissue (n = 5)." (PMID 29849053, 2018). "Moreover, HIF-1α triggers both the TGF-β/Smad and TLR4/MyD88/NF-κB signaling pathways, and the synergy between these pathways could facilitate keloid formation, and selective HIF-1α inhibitors consistently lead to a reduction in collagen levels." (PMID 39114830, 2024).
Klebsiella Infections (3 papers, 2019 to 2022). Infections with bacteria of the genus KLEBSIELLA. "In addition, TLR4–/– × TLR2–/– mice were also observed to be more susceptible to Klebsiella infection." (PMID 32670220, 2020). "As with other bacterial infections, TLR4 signalling plays a prominent role in antibacterial defence against Klebsiella infection." (PMID 30452654, 2019). "Interestingly, cooperative roles of TLR4 and TLR2 signalling are involved in controlling Klebsiella infection because TLR4−/−xTLR2−/− mice are more susceptible to the infection than each of the single knock-out mice." (PMID 30452654, 2019). "Initial observations suggest that TLR4 signalling is indispensable in cells of myeloid origin for the clearance of Klebsiella; however, it cannot be ruled out that other cell types may require TLR4 signalling to aid in the elimination of Klebsiella infections." (PMID 30452654, 2019). "TLR4, TLR2, and TLR9 signaling have been shown to play an important role in Klebsiella infection recognition and defense." (PMID 32670220, 2020). "The lack of TLR4 signalling is associated with a decrease in the levels of IL17 and IL23 in the lungs of infected TLR4−/− mice, which may explain the susceptibility of these mice to Klebsiella infection." (PMID 30452654, 2019). "In cyld knock-down cells, Klebsiella is no longer able to blunt the activation of TLR4/2-MyD88, leading to the production of IL8 following Klebsiella infection." (PMID 30452654, 2019).
Klebsiella pneumonia (3 papers, 2010 to 2021). An pneumonia caused by infection with Klebsiella. "A recent report describes induction of lipocalin 2 in lung cells following infection with Klebsiella pneumonia and points to a toll-like receptor 4 (TLR4)-mediated induction pathway." (PMID 20633248, 2010). "We and others have previously shown that both TLR4 and TLR9 play a critical role in host defense during Klebsiella pneumonia." (PMID 20360853, 2010). "Interestingly, our previous study demonstrated that a capsular polysaccharide isolated from Klebsiella pneumonia induced ROS production and MAPK phosphorylation through TLR4 in J774A.1 macrophages; however, the inhibition of ROS by NAC did not affect the phosphorylation levels of MAPK." (PMID 34944043, 2021).
Legionnaires' disease (3 papers, 2018 to 2021). A pneumonia caused by Legionella pneumophila and other Legionella species, which is characterized by fever, cough, progressive respiratory distress, and which is often accompanied by extrapulmonary manifestations. "Polymorphisms in the genes encoding TLR4, -5 and -6, for example, have been associated with increased risk of Legionnaires’ disease." (PMID 29298342, 2018).
leukocytosis (3 papers, 2010 to 2023). "The heterozygous genotype of the TLR4 896A/G SNP was associated with an increased risk of elevated liver enzyme levels and leukocytosis (p < 0.05)." (PMID 32753695, 2020).
mesothelioma (3 papers, 2022 to 2023). A usually malignant and aggressive neoplasm of the mesothelium which is often associated with exposure to asbestos. "The implications of TLR4 in chronic inflammation and mesothelioma development following asbestos inhalation are hypothesized." (PMID 37894824, 2023). "In contrast, neither TLR4 nor TLR2 stimulation with LPS and bacterial peptidoglycan, respectively, could prevent mesothelioma development (p = 0.62 and 0.91, respectively)." (PMID 36714124, 2022).
myocardial disorder (3 papers, 2022 to 2025). A disorder that affects the muscle tissue of the heart. "In addition to JAK/STAT pathway and TLR4 pathway, whether there are other signaling pathways participating in H2S regulation of ER stress in myocardial disease requires further research." (PMID 37124222, 2023). "A well-known endotoxin, it connects with toll-like receptor 4 (TLR-4) and activates an inflammatory cascade due to myocardial disorders such as dysfunction and remodeling of left ventricular and intensified cardiac muscle cells apoptosis." (PMID 36615748, 2022).
oral diseases (3 papers, 2024 to 2025). "In the “biomarkers-oral diseases” network, TLR4 was associated with 69 oral diseases, and FLT3 was associated with 35 oral diseases." (PMID 40362543, 2025). "The association of SNPs in TLR2 and TLR4 genes with different infectious diseases (including oral diseases) was examined." (PMID 39000094, 2024).
osteomyelitis (3 papers, 2010 to 2022). An acute or chronic inflammation of the bone and its structures due to infection with pyogenic bacteria. "In the majority of patients with implant-associated osteomyelitis, however, T cells expressing TLR1, TLR2 or TLR4 were detected." (PMID 21151520, 2010).
otitis (3 papers, 2015 to 2021). "An analysis of DNA samples from 348 children with a history of two or more AOM episodes and 463 healthy adults showed that the TLR4 299A/A genotype was associated with an otitis-prone condition." (PMID 34360632, 2021). "Susceptibility to otitis might also be impacted by deficiencies in innate immune molecules, such as the microbial pattern recognition receptors Toll-like receptor 4 (TLR4) and Toll-like receptor 2 (TLR2), and the immune signaling molecule MyD88." (PMID 25765466, 2015). "Similarly, a study that compared the expression of TLR4 in middle ear fluid between otitis-prone and non-otitis-prone pediatric OME patients reported that expression of TLR4 mRNA was significantly lower in the otitis-prone group." (PMID 34360632, 2021).
ovarian dysfunction (3 papers, 2022 to 2024). The inability of the ovaries to function. "This study suggested that down-regulation TLR4 and NF-ĸB are important for the effect of up-regulation miRNA-146 expression protects against LPS-induced ovarian dysfunction." (PMID 35531876, 2022). "We constructed and verified the protective effect of miRNA-146 suppressing TLR4/ NF-κB signaling pathways by LPS-induced ovarian dysfunction of POI model." (PMID 35531876, 2022). "To further identify the protective role and function of miRNA-146, we evaluated the level of TLR4 and NF-κB as well as siTLR4 expression, siTLR4 was used for investigation of the relationship between miRNA-146 and TLR4 in LPSL-induced ovarian dysfunction." (PMID 35531876, 2022). "Our findings suggest that NMN exerts its protective effects through the TLR4/NF-κB/MAPK signaling pathways, underscoring its potential as a therapeutic strategy for mitigating inflammation-induced ovarian dysfunction." (PMID 39857373, 2024).
paracoccidioidomycosis (3 papers, 2014 to 2024). A systemic fungal infection caused by Paracoccidioides brasiliensis that is most often seen in immunocompromised patients. "Considering these, we have evaluated the influence of TLR4 on the expression of IL-10 by MDSCs in murine paracoccidioidomycosis." (PMID 39035356, 2024). "Our previous studies in murine paracoccidioidomycosis have shown that the expansion of IL-17 producing cells is controlled by several pathogen recognition receptors (TLR-2, TLR-4, dectin-1) as well as the IL-1R and Toll adaptor protein, MyD88." (PMID 25411790, 2014).
Peripheral Artery Disease (3 papers, 2020 to 2024). "•Key Findings: Pharmaceutical inhibition of the Toll-like receptor 4 pathway might be of clinical significance in patients with peripheral arterial disease, where it could be used as an adjunctive treatment to improve outcomes of treatments at different stages of the disease." (PMID 38510939, 2024).
placental insufficiency (3 papers, 2016 to 2024). Failure of the placenta to deliver an adequate supply of nutrients and oxygen to the fetus. "Another study found that citrulline supplementation improved placental insufficiency, fetal growth and endothelial function by downregulating the TLR4/NF-κB inflammatory pathway." (PMID 38580943, 2024).
polyp (3 papers, 2014 to 2022). A usually exophytic mass attached to the underlying tissue by a broad base or a thin stalk. "An infamous member of this family, TLR4 have been associated with colorectal cancers as well as polyp formation." (PMID 35486660, 2022). "Almost all the genes analyzed in this study revealed decreased gene expression in polyp samples except for TLR4 and MSX1." (PMID 35486660, 2022). "Based on current findings, TLR2 and TLR4 may be upregulated in the process of polyp formation and progression." (PMID 33255933, 2020).